CD38 (CD38 molecule)
Diseases named in the same sentence as CD38 in open-access papers (continued):
Sharing a sentence is not in itself a finding about the gene and the disease.
Sjögren’s syndrome (5 papers, 2019 to 2025). "To date, numerous studies associated CD38 presence with the development of autoimmune reactions and pathogenesis of such conditions as Sjögren’s syndrome, especially in the context of autoantibodies production." (PMID 34681587, 2021).
type 1 diabetes (5 papers, 2018 to 2023). "It is notable in this regard that autoantibodies specific for CD38 have been detected in individuals with type 1 diabetes." (PMID 29881878, 2018). "Interestingly, CD38+ T lymphocytes can suppress proliferation of the CD38- ones, preventing diabetes type 1 during Mycobacterium avium infection." (PMID 36077708, 2022). "In contrast, no disease-specific alterations in the B cell compartment were detected in another study, designed to quantify the expression levels of CD19, CD24, CD27, CD38, IgD and IgM in individuals with type 1 diabetes and age- and sex-matched healthy donors." (PMID 29881878, 2018). "Healthy subjects had higher levels of galectin-10, CD24, CD197, CD196, CD25 and CD45RO and patients with type 1 diabetes had higher levels of CD16, CD45RA, CD274, HLA-DR, CD28, Interleukin (IL)-5R, and CD38." (PMID 37210405, 2023). "To evaluate the phenotypic characteristics of naive and memory B cells in individuals with type 1 diabetes, we developed a polychromatic flow cytometry panel incorporating a viability dye and monoclonal antibodies specific for CD3, CD19, CD21, CD24, CD27, CD38, CD45R/B220, CD95, CXCR3 and IgD." (PMID 29881878, 2018).
age (4 papers, 2024 to 2026). A temporal measurement of the time period elapsed since an identifiable point in the life cycle of an organism. "Therefore, a deeper understanding of the role of CD38 on early transcriptomic and metabolic changes of M‐MDSCs is essential for pharmacological and/or non‐pharmacological interventions for age‐related bone loss and fracture risk." (PMID 39180173, 2024).
B-cell neoplasm (4 papers, 2017 to 2025). A group of heterogeneous lymphoid tumors generally expressing one or more B-cell antigens or representing malignant transformations of B-lymphocytes. "Altogether, this evidence suggests a critical role of extracellular ADO in tumorigenesis and the PD-1/PD-L1 axis dysregulation in CD38-positive cancers; however, this approach has yet to be explored in depth in mature B-cell neoplasm patients." (PMID 39805878, 2025). "CD38 is broadly expressed in non-B cell neoplasms, so next, we investigated the anti-tumor effects of CD38-CAR-T cells in T-ALL and NKTCL models." (PMID 35765110, 2022). "High expression of CD38 in typical MCL suggest that CD38 may contribute to the survival of B cell neoplasm via adhesion molecules such as CD31." (PMID 29246179, 2017). "Further studies are necessary to clarify the pathophysiology of CD38-induced ADO formation and strengthen the link between CD38 expression and the output of ADO and PD-1/PD-L1 in B-cell neoplasms." (PMID 39805878, 2025). "We also propose targeting the CD38-induced-ADO formation pathway, which could serve as a promising therapeutic immune target with multifaceted effects within mature B-cell neoplasms." (PMID 39805878, 2025).
bacterial sepsis (4 papers, 2019 to 2025). "When mice were infected with a lethal dose of methicillin-resistant Staphylococcus aureus (MRSA), DA treatment improved the mortality and bacteremia, and attenuated the cytokine storm, which was associated with decreased CD38+ macrophage populations in the blood and liver." (PMID 34681611, 2021). "The effects of blocking CD38 in bacterial sepsis is contradictory." (PMID 30915370, 2019). "In patients with bacterial sepsis, we confirmed the significant increase in the percentage of CD138+CD38+ PCs compared with HV with a peak value at the end of the first week." (PMID 40155394, 2025).
bladder cancer (4 papers, 2021 to 2025). "Our results found that CD38 is more widely expressed than PD-1/PD-L1 in urothelial carcinoma, which may be one of the reasons why bladder cancer, with high mutational burden, has a low response rate to anti-PD-1 antibody therapy." (PMID 35725444, 2022). "Recently, CD38 + TILs have been associated with longer survival in urinary bladder cancer." (PMID 33629216, 2021). "Next, the ability of intratumoral PD1+CD38+Tim3+ CD8+ T cells to predict the outcome of BCG therapy in bladder cancer was explored." (PMID 37566017, 2023). "We examined CD38 expression in bladder cancer tissues at various stages and the results showed that CD38 was abnormally highly expressed in tumor tissues and was closely associated with tumor progression." (PMID 35725444, 2022). "We further found that CD38 expression was positively correlated with bladder cancer progression, further suggesting that CD38 may be a potential therapeutic target." (PMID 35725444, 2022). "H&E staining of the bladder cancer showed a decrease in tumor volume.In addition, multi-colour flow cytometric analysis confirms that treatment with anti-CD38 antibodies reduces the proportion of infiltrating CD38+ TAMs and increased infiltration of CD8+ T cells in bladder cancer tissue." (PMID 35725444, 2022).
cognitive decline (4 papers, 2025 to 2026). "Within the B cell compartment, IgD− CD27− %lymphocyte appeared to be potentially neuroprotective, whereas CD27+ memory B cells and CD38+ transitional B cells were identified as possible risk factors for cognitive decline." (PMID 40931570, 2025). "Conversely, CD27 expression on memory B cells and CD38 on transitional B cells demonstrated associations with cognitive decline." (PMID 40931570, 2025). "However, the specific cellular sources of CD38 in the brain and the mechanisms by which CD38 influences normal cognitive decline are poorly understood." (PMID 41542058, 2026). "To translate our findings into a potential therapeutic approach for cognitive decline during aging, we evaluated NTX-748, a novel brain-penetrant small molecule CD38 inhibitor." (PMID 41542058, 2026).
colon adenocarcinoma (4 papers, 2018 to 2021). "To analyze whether the anti-mCD38/anti-mPD-1 combination is also effective in other CD38+ tumors, we tested the combination of anti-mPD-1 and anti-mCD38 treatment in mice with established MC38 colon adenocarcinoma tumors, which also express CD38." (PMID 33321969, 2020).
Crohn disease (4 papers, 2015 to 2024). A gastrointestinal disorder characterized by chronic inflammation involving all layers of the intestinal wall, noncaseating granulomas affecting the intestinal wall and regional lymph nodes, and transmural fibrosis. "The expression of CD38 was higher in colon specimens from patients with Crohn’s disease and ulcerative colitis than that from normal controls." (PMID 38982370, 2024). "Also, in recent studies, HLA-DR+CD38+ EM T cells were described in the intestinal mucosa of IBD patients, and specifically in inflamed Crohn’s disease lesions." (PMID 35812429, 2022).
follicular lymphoma (4 papers, 2016 to 2025). Follicular lymphoma is a form of non-Hodgkin lymphoma characterized by a proliferation of B cells whose nodular structure of follicular architecture is preserved. "Importantly, inhibition of EZH2 is currently used in the treatment for other malignancies, including follicular lymphoma; and in MM it can lead to re-expression of CD38." (PMID 38493239, 2024).
Granuloma (4 papers, 2015 to 2025). A compact, organized collection of mature mononuclear phagocytes, which may be but is not necessarily accompanied by accessory features such as necrosis. "Furthermore, macrophages stained with anti-CD38 were associated with P. brasiliensis containing granulomas." (PMID 26317855, 2015). "These Cd38 KO mice have high numbers of granulomas compared to their WT counterparts." (PMID 31455656, 2019). "Histopathology was critical: biopsies demonstrated exuberant granulation tissue with ERG-positive capillaries and a dense CD38-positive plasma cell infiltrate without granulomas." (PMID 40700331, 2025).
head and neck squamous cell carcinoma (4 papers, 2021). A squamous cell carcinoma that arises from any of the following anatomic sites: lip and oral cavity, nasal cavity, paranasal sinuses, pharynx, larynx, and salivary glands. "Moreover, our previous study showed that CD38 deletion upregulates TLR4 expression, and also, there is a paper reporting that CD38 can induce inflammasome-mediated activation of caspase-1 by activating NLRP3 in head and neck squamous cell carcinoma (HNSCC)." (PMID 33860064, 2021). "Tumor Immune Estimation Resource (TIMER) and cBioPortal databases were used to study CD38 level in various tumors and its correlation with tumor immune microenvironment in head and neck squamous cell carcinoma (HNSCC)." (PMID 34211854, 2021).
Hodgkins lymphoma (4 papers, 2015 to 2024). A heterogeneous group of malignant lymphoid neoplasms of B-cell origin characterized histologically by the presence of Hodgkin and Reed-Sternberg (HRS) cells in the vast majority of cases. "Indeed, all of them are capable of binding the CD38 antigen on MM cell lines (RPMI 8226 and LP1) and non-Hodgkin’s lymphoma cells (LB5871-LYMP), while no specific binding was observed on the CD38− cells (K562 cell line) and CD38KO cell lines." (PMID 34727950, 2021).
ischemic heart disease (4 papers, 2017 to 2025). "Higher CD38 levels may potentially contribute to some ischemic heart diseases and other disorders." (PMID 37865667, 2023). "In our study, patients with a higher SYNTAX score, which is an indicative of higher atherosclerotic burden and more severe ischemic heart disease, had a lower number of CD34+KDR+ and CD34+CD38− cells." (PMID 28819363, 2017).
ischemic stroke (4 papers, 2011 to 2025). A stroke disorder caused by obstruction of blood flow to the brain, due to thrombotic (local blood clot formation) or embolic (due to a blood clot or other material traveling from another site) event. "To determine the functional significance of CD38 in ischemic stroke, we compared local and systemic cytokine and chemokine levels, the amount of infiltrating inflammatory cells, the CD38 expression pattern of leukocyte subpopulations, and infarct sizes in wildtype and CD38-deficient mice." (PMID 21625615, 2011). "Conversely, increased levels of B cells (CD27 on IgD– CD38br and CD27 on IgD+ CD38– unswitched memory), CD4 on CD39+ CD4+ (Treg), and DN (CD4–CD8–) AC (TBNK) were linked to higher ischemic stroke risk, indicating hazardous effects." (PMID 40620597, 2025). "The depletion of NAD+ after ischemic stroke can lead to cell death and is associated with the excessive activation of poly-ADP-ribose polymerase (PARP1), as well as an increase in the CD38 enzyme, which consumes NAD+." (PMID 39795876, 2024). "In the case of B cells, except for a decrease in CD38 on transitional B cells post‐ischemic stroke (IVW: β = −0.15, 95% CI −0.30–0.00; p = 0.047), the other 24 traits showed an increase." (PMID 38323746, 2024). "Therefore CD38 might prove a therapeutic target in ischemic stroke." (PMID 21625615, 2011).
kidney transplant (4 papers, 2021 to 2025). A surgical procedure in which one or both kidneys from a donor are implanted into a recipient. "A recent randomized controlled trial demonstrated that treatment with anti-CD38 monoclonal antibody felzartamab suppressed antibody-mediated rejection (ABMR) in kidney transplant patients but with recurrence after treatment in some patients." (PMID 40301559, 2025). "Molecular analyses of longitudinal kidney biopsies from a phase 2 trial testing an anti-CD38 antibody for kidney transplant rejection show temporary suppression of antibody-mediated rejection during treatment, with molecular recurrence at 52 weeks." (PMID 40301559, 2025). "Similarly, in B cells, the presence of CD24 on IgD+ CD38- unsw mem cells (OR = 1.2797, 95% CI = 1.0090 to 1.6231, p = 0.0419) and IgD on IgD+ CD38- cells (OR = 1.6871, 95% CI = 1.2058 to 2.3605, p = 0.0022) has also been shown to be associated with an increased risk of prostatitis." (PMID 39323879, 2024).
latent infection (4 papers, 2010 to 2022). "The results of our conventional analyses show the performance of CD27, CD38, HLA-DR and Ki-67 to discriminate active disease from latent infection." (PMID 35935194, 2022). "THY-1 is expressed in many types of cells that can be productively infected by HCMV as well as CD34+/CD38- stem cells, a putative cellular reservoir for latent infection." (PMID 26147640, 2015). "In this paper, we aim to study the expression of the CD27, CD38, HLA-DR and Ki-67 markers in Mtb-specific CD4+ T-cells by performing a side by side comparison of their performance on characterizing active disease and latent infection." (PMID 35935194, 2022). "Notably, CD34+CD38- HSCs demonstrate elevated sensitivity to cell-cycle arrest following HTLV-1 infection in comparison to more mature CD34+CD38+ HPCs, suggesting that HTLV-1 may target stem cells to facilitate a latent infection in vivo by inducing cell cycle arrest to induce cellular quiescence." (PMID 20132553, 2010). "In contrast to EBNA-2 PRS-specific CD4+ T-cells during latent infection, perforin and granzyme B expression by NIL-specific CD4+ T-cells was in the absence of continued activation as shown by their lack of CD38 expression." (PMID 34882759, 2021).
lymphoid neoplasm (4 papers, 2021 to 2023). A neoplasm composed of a lymphocytic cell population which is usually malignant (clonal) by molecular genetic and/or immunophenotypic analysis. "The XABCL generated from the TNBC biopsy resulted in a lymphocytic tumor; XABCL-LCL was CD19+, CD20+, CD21−, and CD38+, an activated germinal center B-cell phenotype." (PMID 34868006, 2021). "Thus, caution must be exercised when evaluating the clinical benefit of anti-CD38 and ATRA to patients with lymphoid neoplasms, particularly for R/R patients." (PMID 35765110, 2022).
monoclonal gammopathies (4 papers, 2017 to 2021). "In line with the literature, the immunohistochemistry data showed that CD38 was expressed at high levels by PCs of patients with monoclonal gammopathies." (PMID 28915615, 2017). "This study firstly defines by flow cytometry and immunohistochemistry the expression of CD38 by bone marrow cells in a cohort of patients with MM and indolent monoclonal gammopathies." (PMID 28915615, 2017).
myocardial ischemia (4 papers, 2016 to 2022). A disorder of cardiac function caused by insufficient blood flow to the muscle tissue of the heart. "The findings of this study will broaden our understanding of the roles of CD38 in physiological and pathological conditions in the heart and provide new insights into the mechanisms of the myocardial ischemia/reperfusion injury." (PMID 27547294, 2016).
NK/T cell lymphoma (4 papers, 2021 to 2024). "Wang L and colleagues demonstrated that 95% of NK/T cell lymphoma (NKTCL) cases were CD38 positive and half had high CD38 expression, which was significantly correlated with adverse results, indicating the potential role of CD38 as a therapeutic target in ENKTCL." (PMID 35515118, 2022).
prostate tumor (4 papers, 2009 to 2025). "CD38, a druggable ectoenzyme, has been shown to be expressed on diverse prostate tumor-infiltrating immune cells (TIICs), and the CD38+ TIIC density is independently related to worse overall survival of patients with PC." (PMID 37719710, 2023). "When comparing gene expression of metastatic prostate tumor samples recovered from autopsies to normal prostate, we identified CD38 as significantly downregulated in metastases." (PMID 30258629, 2018).
renal cell carcinoma (4 papers, 2024 to 2026). "Additionally, among renal cell carcinoma (RCC) patients (n = 36) receiving multiple aPD-1 monotherapy or combination treatments, the greater the increase in HLA-DR+CD38+CD8+ T cells post-treatment, the more significant the reduction in tumor size was observed." (PMID 41535994, 2026). "In the Human Protein Atlas, CD38 protein expression in both renal cell carcinoma (RCC) and urothelial cancer is absent, but RNA levels have found low levels of expression, likely reflecting the presence of CD38-expressing immune cells." (PMID 39207194, 2024).
renal fibrosis (4 papers, 2022 to 2025). A final common manifestation of a wide variety of chronic kidney diseases characterized by glomerulosclerosis and tubulointerstitial fibrosis. "Our results indicate that a macrophage subset with high CD38 expression is closely linked to renal fibrosis following AKI in both mouse model and AKI patients." (PMID 40349105, 2025). "They identified that CD38 high-expression (CD38hi) macrophage subsets were closely associated with renal fibrosis." (PMID 41465886, 2025). "Deletion or inhibition of CD38 reduced obstruction-associated renal fibrosis and inflammation." (PMID 36804530, 2023). "These CD38hi macrophages, derived from resident macrophages via Csf1 signaling, secrete the NAD-depleting enzyme CD38, inducing senescence in renal tubular cells and promoting chronic inflammation and renal fibrosis." (PMID 40349105, 2025). "Histological examination showed that genetic deletion of CD38 ameliorated UUO-induced renal fibrosis, as evidenced by the decrease in collagen accumulation and αSMA-positive cells." (PMID 36804530, 2023). "We uncovered the dysregulation of NAD+ metabolism in obstructive nephropathy and found that NADase CD38 promoted obstruction-induced renal fibrosis and kidney inflammation." (PMID 36804530, 2023). "We learned that CD38 was mainly expressed in endothelial cells, macrophages, and dendritic cells during renal fibrosis." (PMID 36804530, 2023). "CD38 and NAD+ decline are also associated with activated NF-κB signaling, which is involved in the development of renal fibrosis." (PMID 36804530, 2023). "We found that CD38 was partially expressed in immune cells during UUO-induced renal fibrosis, half of which were CD11b+ F4/80+ macrophages, suggesting that a subset of CD38-positive macrophages emerged during the fibrotic process." (PMID 36804530, 2023). "•CD38 deletion or inhibition mitigated obstruction-induced renal fibrosis." (PMID 36804530, 2023). "Thus, our work not only provides an enriched resource for future investigations of obstructive nephropathy but also establishes CD38-mediated NAD+ decline as a potential therapeutic target for obstruction-induced renal fibrosis." (PMID 36804530, 2023). "Collectively, these results suggest that CD38 promotes UUO-induced renal fibrosis." (PMID 36804530, 2023). "Next, we asked the mechanisms by which CD38 and NAD+ decline promoted renal fibrosis induced by obstruction." (PMID 36804530, 2023). "CD38 deletion or inhibition and NAD+ supplementation restored NAD+ levels and ameliorated UUO-induced renal fibrosis, partially through the mechanism of reducing kidney inflammation." (PMID 36804530, 2023). "CD38 deletion or inhibition and NAD+ supplementation mitigated UUO-induced renal fibrosis, partially through the mechanism of reducing kidney inflammation." (PMID 36804530, 2023). "Having uncovered the NAD+-degrading and profibrotic role of CD38 in obstructive nephropathy, we then asked whether NAD+ supplementation can confer protective effects against obstruction-induced renal fibrosis." (PMID 36804530, 2023). "Taken together, these results indicate that targeting CD38 and NAD+ metabolism reduces kidney inflammation, partially by suppressing the infiltration of immune cells and NF-κB signaling, thus mitigating obstruction-induced renal fibrosis." (PMID 36804530, 2023). "Genetic deletion or pharmacological inhibition of CD38 as well as NAD+ supplementation significantly recovered NAD+ levels in obstructed kidneys and reduced obstruction-induced renal fibrosis, partially through the mechanisms of blunting the recruitment of immune cells and NF-κB signaling." (PMID 36804530, 2023). "Importantly, the major NADase CD38 was strongly induced in human and experimental obstructive nephropathy, and its deletion or inhibition recovered renal NAD+ levels and ameliorated UUO-induced renal fibrosis." (PMID 36804530, 2023).